XBP1 (X-box binding protein 1)
Diseases named in the same sentence as XBP1 in open-access papers (continued):
Sharing a sentence is not in itself a finding about the gene and the disease.
tumor (continued). "Blocking TGFβ-receptor signaling with SB-431541 significantly reduced mRNA-expression of ER-stress markers DDIT3, spliced XBP1 and HSPA5 in stellate cells co-cultured with tumor cells using transwells." (PMID 33103995, 2020). "For example, ER proteins such as XBP1, PERK, ATF6 and ATF4 that are involved in ER stress have been reported to participate in tumor growth and metastasis." (PMID 33014334, 2020). "We applied Western blot to examine the expression of XBP1 and NAT1 in GBC and matched adjacent non-tumor tissues." (PMID 32793479, 2020). "We have identified the IRE1α/XBP1 axis as a critical signaling pathway in macrophage polarization to a mixed IIS phenotype, PD-L1 expression, and tumor growth." (PMID 32520957, 2020). "XBP1-positive and NAT1-negative expression was positively related to larger tumor size (>3 cm) in GBC and AC." (PMID 32793479, 2020). "Further study demonstrated that LUCRC can regulate the expression of the protein folding chaperone Bip and induce the splicing of XBP1 from XBP1u (unspliced) to XBP1s (spliced), resulting in activation of UPR to promote tumor progression." (PMID 33267910, 2020). "This study also demonstrated that XBP1 is activated by toll-like receptor (TLR) and myeloid differentiation primary response gene 88 (MyD88) signaling in tumor-bearing mice." (PMID 32635462, 2020). "Another study showed that XBP1 depletion in TNBC cell line models inhibits tumor growth, decreases tumor relapse and the CD44highCD24low population of cancer stem cells, known to mediate cancer recurrence." (PMID 32516978, 2020). "The Venus protein signal was significantly higher in tumor-infiltrating CD11b+ cells relative to those in control tissues, suggesting a concurrent UPR signaling with XBP1 splicing in the TME only." (PMID 32520957, 2020). "Nonetheless, they observed elevated expression of KDM4B, XBP1, AR, MYB, and SPDEF in early neoplasias compared to normal which were also elevated in our profile." (PMID 31248446, 2019). "(C, D) PCR fragments of total Xbp1 and spliced Xbp1 of TC1 (C) and B16F10 (D) tumor cells +/- IFNy for 24 h." (PMID 31196219, 2019). "It is the spliced form of XBP1 that is known to act as a potent transcriptional regulator of UPR genes such as BIP, and a promoter of tumor cell survival." (PMID 29311669, 2018). "In this study, we also found that IRE1α-XBP1 inhibitors exerted anti-tumor activity against ES, in part through their inhibition of the UPR and IRE1α-XBP1 pathway." (PMID 29581854, 2018). "This allowed us to demonstrate the antagonistic roles of XBP1 mRNA splicing and RIDD on tumor outcomes." (PMID 29311133, 2018). "TUN at a dose of 10μg was able to increase the expression of UPR genes (Grp78, PERK, XBP1, and ATF6) and IAP protein Survivin, which indicates the role of ERS in tumor promotion." (PMID 30326660, 2018). "The correlation between the NCK1-AS1 expression and these transcription factors E2F1, XBP1 and SP1 were performed and correlation analysis revealed that NCK1-AS1 has a significantly positive correlation with SP1 in TCGA CESC Tumor data set." (PMID 29416014, 2018). "Recent work from our laboratory has shown that paclitaxel induces XBP1 splicing in TNBC and that MKC8866 significantly sensitizes TNBC tumours to paclitaxel in a murine xenograft model." (PMID 30248920, 2018). "This approach allowed us to demonstrate the antagonistic roles of XBP1 mRNA splicing and RIDD on tumor outcomes, mainly through selective remodeling of the tumor stroma." (PMID 29311133, 2018). "Inhibition of the IRE1α/XBP-1 pathway by toyocamycin, salicylaldehyde analogues and STF 083010 induced apoptosis in various tumours." (PMID 29415493, 2018).
tumor (continued). "In parallel, an autophagy-related cytoprotective role of IRE1 and its downstream target X-box binding protein 1 (XBP1) against hypoxia and tumor growth has only recently emerged." (PMID 30250843, 2018). "We further demonstrate that both adipocyte-induced oxidative stress and HO-1 overexpression result in splicing of the X-box protein XBP1 and activation of survival pathways involving survivin (BIRC5) and Bcl-xl in tumor cells." (PMID 29311669, 2018). "Our work demonstrates that in GBM IRE1, downstream signals, including XBP1 mRNA splicing and RIDD, dictate tumor phenotypes and patient outcomes." (PMID 29311133, 2018). "In malignant tumour B cells, STING also induces an ER stress response through the IRE-1 / XBP-1 (X-Box binding protein 1) pathway." (PMID 28596706, 2017). "LOXL2-activated XBP1 directly promotes upregulation of EMT-TFs that in turn would favour the high aggressiveness and metastasis of those tumour types." (PMID 28332555, 2017). "In the current studies, we investigated the immunomodulatory effects of lenalidomide on XBP1-specific CTL phenotype and anti-tumor activities." (PMID 27668268, 2015). "XBP1 is a critical transcription activator participating in the UPR, a cellular adaptive mechanism that occurs in majority of tumors, and it allows the tumor cell to survive under stress conditions by increasing its protein folding capacity." (PMID 27668268, 2015). "Moreover, studies have found that XBP1 is overexpressed in a variety of solid tumors by various analyses, i.e. genome-wide profiling, flow cytometry, and immunohistochemistry; and is required for functions including tumor cell growth and survival and proliferation under hypoxic conditions." (PMID 27668268, 2015). "Luminal A tumours tend to be low grade tumours that are characterised by over expression of ER-activating genes including LIV1, CCND1, FOXA1, XBP1, GATA3 and Bcl-2." (PMID 24392136, 2014). "In the case of BRCA1 vs BRCA2 tumours, only four of the influential TFs (GATA3, ESR1, FOXA1 and XBP1) were identified as differentially expressed." (PMID 25521701, 2014). "The results showed that restored XBP-1 expression by transfecting pCMV-XL5-XBP-1s attenuated agomir-214 mediated XBP-1 suppression and tumor suppressor effects in vitro and in vivo." (PMID 22359598, 2012). "All 10 DCIS sections stained positive in tumour regions for GRP78, 8 of 10 had detectable nuclear XBP1 staining." (PMID 19861963, 2009). "IRE1 knockdown but not enzymatic IRE1 inhibition or XBP1 disruption attenuated cell cycle progression and tumor growth." (PMID 40208872, 2025). "Muscle-specific deletion of XBP1 reduced the amounts of ubiquitinated proteins, levels of multiple components of the UPS and autophagy, strongly correlating with the preservation of muscle mass in KPC tumor-bearing mice." (PMID 40655023, 2025). "Research has also demonstrated that XBP1, a downstream effector of IRE1, can facilitate angiogenesis independently of VEGF, indicating the presence of alternative pathways through which IRE1 regulates tumor vascularization." (PMID 41209558, 2025). "Genetic targeting of XBP1 or pharmacological inhibition of IRE1α kinase activity using KIRA8 led to reduced cholesterol levels and MDSC abundance, resulting in activation of effective anti-tumor immunity in mouse cancer models." (PMID 41372991, 2025). "Using UPR inhibitors and in loss-of-function experiments for transcription factors such as, XBP1, ATF4 and ATF6, we find that C5aR1 expression is complementarily regulated by multiple UPR pathways; highlighting the strong dependence of tumour cells on UPR-dependent C5aR1 signalling." (PMID 40695778, 2025). "We utilized qRT-PCR to validate increased expression of various transcripts related to the IRE1α/XBP1 arm of the UPR, such as IRE1 (gene name: Ern1), Xbp1, Dnajb9, Edem1, and CHOP (gene name: Ddit3) in GA muscle of KPC tumor-bearing mice compared to control mice." (PMID 40655023, 2025).
tumor (continued). "Furthermore, mRNA levels of Xbp1 and its known transcriptional target Dnajb9 were reduced in GA muscle of KPC tumor-bearing Xbp1mKO mice compared with GA muscle of KPC tumor-bearing Xbp1fl/fl mice." (PMID 40655023, 2025). "While the mechanisms of action were not investigated, we showed that targeted deletion of XBP1 inhibits muscle wasting in response to LLC tumor growth." (PMID 40655023, 2025). "However, XBP1, a transcription factor of IRE1α-XBP1 signalling, inhibits the CD4+ T-cell-mediated immune response and promotes tumour progression." (PMID 38297380, 2024). "Low expression of XBP1, including XBP1s and XBP1u (downstream targets of IRE1), can inhibit the Warburg effect in prolactinoma GH3 cells by downregulating PKM2, and fulvestrant exerts its tumor-suppressive effects through this pathway." (PMID 39080273, 2024). "Then, pharmacological ER stress induction by HA15 exerted prominent anti-tumor effect in immunocompetent mice and was highly dependent on CD8+T cells, paralleled with the reshape of immune cells in tumor microenvironment via tumorous IRE1α-XBP1 signal." (PMID 38291473, 2024). "In addition, a low dose of TM decreases exosome production in carcinoma cells, and Xbp1 depletion significantly decreases the numbers of exosomes and exosome markers, such as TSG101 and CD63, produced from tumor cells." (PMID 37524131, 2023). "In addition, lipid peroxidation byproducts 4-HNE in DCs would activate X-box binding protein 1 (XBP1) to induce ER stress, which eventually resulted in the inability of DCs to present tumor antigens and stimulate CD8+ T cell responses." (PMID 38259464, 2023). "In addition to IRE1α-XBP1, the TME was found to induce PERK expression in tumor macrophages and promote immunosuppressive activity." (PMID 37067519, 2023). "In obese mice, the IRE1α-XBP1 axis represses AAM polarization, and in nonobese mice, it contributes to the mixed phenotype of tumor-associated macrophages, regulating the expression of both CAM and AAM markers." (PMID 36475773, 2023). "Notably, among the three established UPR pathways involved in persistent ERS resulting from the complex tumor microenvironment (TME), IRE1α-XBP1 signaling is the most conserved pathway and has been implicated in tumorigenesis and progression." (PMID 36092910, 2022). "Tumor cell microenvironments, such as hypoxia and nutrient deprivation, induce ER stress, thereby activating the UPR stress signaling pathways including the IRE1α/XBP1-s axis." (PMID 35269888, 2022). "These role of XBP1 to shape non-inflamed tumour microenvironment in BC was validated in GSE25065 and TCGA dataset." (PMID 35543228, 2022). "Furthermore, restoration of the IRE1 signaling pathway, through the expression of an active form of XBP1, inhibited GCB-DLBCL tumor growth in a mouse xenograft model." (PMID 35626128, 2022). "Besides, X-box binding protein 1 (XBP1), a key protein in UPR, is induced in a hypoxia environment and promotes tumor growth, implying that hypoxia coupled with ER stress plays certain roles in tumor development." (PMID 35798726, 2022). "Our observations indicating activated UPR signaling, regulated by IRE1α/XBP1 in ALDH+ CSCs, suggest that this mechanism may be necessary to protect ALDH+ cells from ER stress in the tumor microenvironment." (PMID 35349489, 2022). "The result indicated that the anti-tumor function was a result of knocking out XBP1 from TAMs but not from tumor cells." (PMID 34667145, 2021). "Our results support a model in which ER stress, in general, counteracts the development of Notch-dependent germline tumours and suggest that the IRE-1/XBP-1 branch of UPR may be one of the arms involved in this counterbalance." (PMID 34555015, 2021). "Conversely, mice harboring TAMs lacking XBP1 showed reduced orthotopic tumor formation (5/5 vs. 3/5) and liver metastasis (4/5 vs. 1/5) compared with control mice." (PMID 34667145, 2021).
tumor (continued). "Mice lacking the expression of IRE1α or XBP1 in NK cells had increased tumour burden using the B16 melanoma tumour model." (PMID 34090499, 2021). "Although it was associated with the stage score, neither IRE1α nor cytosolic XBP1 expression levels were correlated with lymph node (p values 0.78 and 0.58), distant metastasis (p values 0.49 and 0.77) or tumor scores (p values 0.49 and 0.77) in RMS patients." (PMID 34638414, 2021). "Similarly, XBP1-positive expression and NAT1-negative expression were closely related to poorly differentiated type, larger tumor mass, advanced TNM stage (III + IV), lymph node metastasis, invasion, and only receiving biopsy in AC (all P < 0.05)." (PMID 32793479, 2020). "B16.F10 tumor–bearing mice with conditional Ern1-KO but not Xbp1-KO macrophages had significantly greater survival than their fl/fl controls." (PMID 32520957, 2020). "(D) Ratio of spliced to unspliced XBP1 in liver tissue from healthy mice; and tumor tissue and surrounding non-tumoral tissue from mice with DEN-induced HCC, treated with 4μ8C." (PMID 33103995, 2020). "Here we show that the UPR and the IRE1α/XBP1 axis are activated in macrophages during tumor growth and that the CKO of IRE1α in macrophages regulates the acquisition of a mixed IIS phenotype and is also sufficient to restrain tumor development in vivo." (PMID 32520957, 2020). "This confirmed that tumor cells secrete factors that induce mRNA-expression of EIF2AK3, DDIT3, HSPA5, spliced XBP1, and HSPA5, as well as protein expression of p-IRE1α in hepatic stellate cells co-cultured with tumor cells, indicating the presence of ER-stress." (PMID 33103995, 2020). "Western blot on whole tissue samples – containing both tumor and non-tumoral tissue – also confirmed a significant decrease of XBP1-splicing after treatment with 4μ8C." (PMID 33103995, 2020). "In tumor bearing mice, the ER stress markers such as p-eIF2α, CHOP, IRE1α, XBP1, ATF6, DR5, GRP78, GRP94, GADD34, and sXBP1 were found to be substantially elevated as well as correlated with increased ubiquitylated protein levels and heightened expression of E3 ligases: MAFBx, MuRF1, TRAF6." (PMID 31817027, 2019). "ATF6 and XBP1 are two most important factors mediating the UPR and their downregulation could induce tumour cell death in aggressive cancers like PDAC, thereby acting as a regulatory mechanism in the overall process of tumourigenesis." (PMID 31795960, 2019). "The transcriptional complex of XBP1 with HIF1α elevates the expression of pyruvate dehydrogenase kinase 1 (PDK1) and glucose transporter 1 (GLUT1) that are the downstream genes of HIF1α, which facilitates tumor development and invasiveness of TNBC." (PMID 31739582, 2019). "We found that all the tested XBP1 target genes were upregulated in tumor tissues compared to nontumor tissues." (PMID 31320625, 2019). "Interestingly, treatment of adipocyte-tumor cell co-cultures with Isoproterenol, an inducer of lipolysis, increased splicing of XBP1 and augmented BIP expression, indicating the importance of adipocyte-supplied lipids in ER stress induction in tumor cells." (PMID 29311669, 2018). "Several IRE1 RNase inhibitors that block XBP1 splicing and RIDD; MKC3946, 3-methoxy-6-bromosalicylaldehyde, 4μ8C, STF-083010, and Toyocamycin, have shown promise in multiple myeloma models, where XBP1s is known to be important for tumour progression." (PMID 30248920, 2018). "This allows ESR1+ tumours to achieve estrogen-independent growth and helps to explain why both XBP1 isoforms can drive ESR1+ cancer, but not TNBC." (PMID 30248920, 2018). "Transcriptional profiling classified the Ta tumours as luminal (high expression of luminal markers such as GATA3, PPARG, FOXA1 and XBP1 as well as differentiation markers such as UPK1A and KRT20) as well as non-aggressive (high expression of SKAP2, FABP4, MBNL2 and ID1)." (PMID 28916750, 2017).
tumor (continued). "Consistently, tumor-infiltrating DCs lacking XBP1 acquire immunostimulatory and antitumoral characteristics in vivo." (PMID 29430279, 2017). "Compared to non-memory cells, the memory cells of XBP1-CTL demonstrated significantly greater anti-tumor activities, measured by granzyme B upregulation and IFN-γ production." (PMID 27668268, 2015). "In contrast, these studies indicate that lenalidomide does not appear to directly affect the expression levels of the intracellular XBP1 target antigens, nor extracellular activation/inhibitory molecules on tumor cells." (PMID 27668268, 2015). "The XBP1 mRNA expression was not correlated to age, gender, anatomic location, or tumor size statistically significant." (PMID 26633383, 2015). "Result show that miR-214 and miR-199a-3p/5p was significantly down-regulated in HepG2 cells after TG and TM treatments or anoxia, further suggesting that UPR activated XBP-1 or mTOR and ERK pathway to protect tumor cell survival though suppression of the miR-199a2/214 cluster in HCC." (PMID 22359598, 2012). "In support of the hypothesis that ER stress signals can be tumor suppressive, recent findings showed that ATF6, ATF4 and XBP-1 signaling can suppress H-Ras induced transformation in melanocytes." (PMID 17637831, 2007). "In tissue stem cells, the high communication activity of CD99 may be associated with cell migration and invasiveness in the tumour microenvironment, promoting tumour cell spread and metastasis, suggesting that XBP1, TRPC6 and TTC28 may promote tumour development." (PMID 40046334, 2025). "The high interaction of tissue stem cells with collagen may affect the tumour microenvironment by promoting extracellular matrix synthesis and degradation, and influencing tumour growth and angiogenesis, suggesting that XBP1, TRPC6 and TTC28 may influence tumour growth and angiogenesis." (PMID 40046334, 2025). "We surprisingly found that the deletion of Atg16l1 led to a significantly increased tumor prevalence in Atg16l1/Xbp1/Rnaseh2bΔIEC mice (no functional autophagy present to compensate for defective UPR) compared to Xbp1/Rnaseh2bΔIEC mice (autophagy compensates for the defective UPR) of the same age." (PMID 41057521, 2025). "Whereas tumor cDC1s from control mice displayed high levels of Xbp1 spliced mRNA, tumor cDC1s isolated from XBP1ΔDCIRE1truncDC mice were unable to induce Xbp1 splicing due to the lack of a functional IRE1 RNase domain." (PMID 37346037, 2023). "Consistent with expectations, the upregulation of inhibitory receptors (PD1, TIGIT) and XBP1 was observed when coculturing CD8+ T cells with the supernatant of BTC cells, suggesting that ER stress and exhausted CD8+ T cells were induced and formed in the tumor microenvironment." (PMID 35982235, 2022). "However, there might be some experimental challenges in extracting B cells from the tumor tissues of LUAD patients and in distinguishing the isoforms of XBP1 for identification of its specific function." (PMID 36092910, 2022). "Subsequently, we investigated the correlation between XBP1 expression and TILs in LUAD and found that XBP1 expression had a significant correlation with the infiltration of B cells and PCs but not with tumor purity, which suggests that XBP1 was mainly expressed in B cells and not in cancer cells." (PMID 36092910, 2022). "In summary, XBP1 expression level obviously increased in BC patients, especially in patients with luminal BC, and high XBP1 expression indicated high chemosensitivity, good prognosis, and a non-inflamed tumour microenvironment in BC patients." (PMID 35543228, 2022). "In the tumour microenvironment, however, the excessive amounts of cholesterol produced by tumour cells enter TILs’ cytoplasm, accumulate in the ER, and could overwhelm ACAT activity, thereby activating XBP1 and the transcription of inhibitory checkpoints." (PMID 34202553, 2021).